FDX1 (ferredoxin 1)
Diseases named in the same sentence as FDX1 in open-access papers (continued):
Sharing a sentence is not in itself a finding about the gene and the disease.
cancer (continued). "Second, while prior studies have explored cuproptosis-related genes across cancers, our work emphasizes immune correlation and identifies distinctive gene-immune interactions—particularly involving FDX1 and SLC31A1—which were underreported in previous literature." (PMID 40601654, 2025). "A strong correlation has been detected between FDX1 and cancer." (PMID 38918694, 2024). "Despite accumulating evidence supporting a vital role for FDX1 in tumorigenesis in certain cancers, its functional significance in cancers, particularly in LUAD, remains unclear." (PMID 38802900, 2024). "Additionally, FDX1 expression has been positively correlated with the presence of most cancer immune cells." (PMID 39702350, 2024). "The boxplots indicated that the gene level of FDX1 was dysregulated across all forms of cancer." (PMID 38671021, 2024). "FDX1 expression increased at certain stages of various types of cancer." (PMID 37298135, 2023). "We therefore speculated that the cancer cells in the high-FDX1 expression group may have had upregulated the immune-suppressive checkpoints to evade attack by immune cells." (PMID 37301546, 2023). "In addition, the high-FDX1 expression group had higher Estimation of Stromal and Immune cells in malignant tumor tissues using Expression data, stromal, and immune scores (p<0.001)." (PMID 37301546, 2023). "Based on potential molecular mechanisms, it is unknown whether FDX1 plays a role in the pathogenesis of multiple types of cancer." (PMID 37298135, 2023). "Although the analysis of public bioinformatic database has some limitations due to the limited clinical and pathological information, it also indicates FDX1 is expected to become a potential target for cancer treatment and a biomarker for evaluating prognosis in the future." (PMID 36925927, 2023). "DNAss and RNAss were used to validate the relationship between FDX1 level and cancer stemness." (PMID 37298135, 2023). "Expression levels of FDX1 in 33 cancers were analyzed from the TCGA database." (PMID 36173462, 2023). "Finally, we investigated the effect of FDX1 expression in KIRC (kidney renal clear cell carcinoma) to verify our findings in human cancer." (PMID 37193786, 2023). "Collectively, our study applied pan-cancer bioinformatics analysis and found that FDX1 might be considered a potential poor prognosis biomarker and immunotherapy predictor in LGG." (PMID 36825202, 2023). "The expression of FDX1 kept increasing in certain stages across various types of cancer." (PMID 37298135, 2023). "Collectively, these findings propose that FDX1 could serve as a novel and valuable biomarker and represent an immunotherapeutic target for augmenting immune responses in various human cancers when used in combination with immune checkpoint inhibitors." (PMID 37298135, 2023). "In the current study, we explored the role of FDX1 in human pan-cancer by transcritomic analysis." (PMID 36825202, 2023). "However, FDX1 expression was shown to be higher in cancer samples compared with healthy samples in STAD (p < 0.001)." (PMID 37298135, 2023). "Several databases examined FDX1 expression in human cancers to determine its prognostic value." (PMID 37193786, 2023). "All these results indicated that the FDX1 expression level might be regulated through different approaches in various cancer types." (PMID 36766692, 2023). "Nevertheless, much less is known about the role of FDX1 in cancer, especially in ccRCC." (PMID 36766692, 2023). "In our study, we comprehensively and systematically analyzed FDX1 in thirty-three distinct cancer types via the TCGA, GEO, and CAPTAC datasets, as well as the molecular functions of gene expression, somatic mutations, methylated DNA, and phosphorylated proteins." (PMID 37298135, 2023). "The results indicate that FDX1 plays an important role in the cancer immune microenvironment." (PMID 37301546, 2023).
cancer (continued). "In the analysis conducted using the TCGA database, a negative correlation was observed between FDX1 levels and cancer-associated fibroblasts across multiple cancer types." (PMID 37298135, 2023). "Further experimental validation is needed to determine whether FDX1 can be used as a potential target and predictor for cancer immunotherapy." (PMID 37193786, 2023). "Through GO/KEGG enrichment analysis, we identified that FDX1 may be involved in the regulation of cancer through pathways related to “cancers” and “metabolic pathways”." (PMID 37298135, 2023). "FDX1 may be related to glucose and lactic acid metabolic disorder in cancer.FDX1 may participate in the steroid synthesis to regulate CYP450 affecting the development of some hormone-related cancers." (PMID 36925927, 2023). "All above results illustrated that FDX1 expression might act as an excellent clinical prognostic value for patients with certain cancers." (PMID 37298135, 2023). "Therefore, a comprehensive and systematic analysis of FDX1 across multiple cancer types was conducted." (PMID 37298135, 2023). "FDX1 was low expressed in most cancers, such as BRCA, KICH, and COAD." (PMID 36173462, 2023). "The molecular mechanisms involved in the pathogenesis of multiple cancers may be similar to those involved in FDX1." (PMID 37298135, 2023). "It is unknown whether FDX1 plays a role in the pathogenesis of multiple types of cancer across potential molecular mechanisms." (PMID 37298135, 2023). "The association between FDX1 and TME might explain another reason for FDX1's prognostic significance in various cancers." (PMID 37193786, 2023). "In addition, we also obtained box plots of FDX1 expression in different types of cancer across the R package." (PMID 37298135, 2023). "In our study, we investigated the FDX1 expression pattern in TCGA pan-cancer." (PMID 36825202, 2023). "A pan-cancer analysis revealed that transcription and protein expression of FDX1 was significantly reduced in most cancer types, and furthermore, FDX1 expression levels were closely correlated with immune cell infiltration, immune checkpoint genes, and immune regulatory genes to some extent." (PMID 37035162, 2023). "On the cBioPortal website, FDX1 genomic alterations were analyzed in human cancers." (PMID 37193786, 2023). "In general, FDX1 was expressed differently in different types of cancer in humans." (PMID 37193786, 2023). "It is hypothesized that regulating FDX1 using a combination of immune checkpoint inhibitors and chemotherapy drugs can contribute to the development of antitumor drugs for various types of cancers." (PMID 37298135, 2023). "Our first finding was that patients’ age may be a vital factor in FDX1 expression, and we compared the expression of FDX1 in 33 types of cancer and found that the expression of FDX1 across various types of cancers differed according to the patients’ age." (PMID 37298135, 2023). "The results presented above indicated that FDX1 could serve as a prognostic biomarker for pan-cancer." (PMID 37193786, 2023). "Potentially serving as a pan-cancer biomarker or a new immunotherapy target, FDX1 may have a significant impact on predicting immunotherapy response or helpful in achieving promising therapeutic outcomes." (PMID 37193786, 2023). "Many studies have shown that FDX1 was closely related to immune regulation in Pan-cancer." (PMID 36755576, 2023). "Furthermore, FDX1 expression was significantly associated with MSI in 8 cancers and TMB in 10 cancers." (PMID 36210836, 2022). "Patients with genomic instability of FDX1 had the disposition to poor survival in cancer patients." (PMID 36226187, 2022). "These speculations still require further experimental confirmation to test whether FDX1 may become a potential target and predictor of cancer immunotherapy." (PMID 35991547, 2022).
cancer (continued). "Furthermore, survival outcome via the log-rank test illustrated FDX1 upregulated expression was predominantly associated with KIRC, indicating the longest survival significance among cancers." (PMID 36186457, 2022). "Indeed, elevated FDX1 gene expression was identified as a robust biomarker for elesclomol-induced toxicity across a panel of more than 700 cancer cell lines." (PMID 36017664, 2022). "Moreover, we also investigated the expression of FDX1 in different cancer cell lines using the CCLE database." (PMID 36210836, 2022). "We first assessed the expression and prognostic significance of FDX1 in pan-cancer." (PMID 36210836, 2022). "Single-gene GSEA was used to identify relevant pathways affected by FDX1 expression in pan-cancer." (PMID 35991547, 2022). "FDX1 expression was significantly associated with DNA methylation in 6 cancers, while there was a correlation between FDX1 expression and RNA methylation-related genes and MMR gene in most cancers." (PMID 36210836, 2022). "In addition, we found that high expression of most of these genes predicted poor prognosis in cancer patients, such as FDX1 in LUAD and LGG; LITP1 in SKCM and UVM; DLAT in BLCA and LIHC; and CDKN2A in KICH, ACC, THCA, LIHC, LIHC, KIRC UCEC and COAD." (PMID 36581992, 2022). "To determine whether low FDX1 gene expression in cancer is a generalized phenomenon, we analyzed the FDX1 gene expression in pan-cancer samples and compared it to that in adjacent healthy tissue samples in the TCGA dataset." (PMID 36225932, 2022). "In addition, FDX1 can augment the copper-dependent cell death induced by elesclomol and can offer a new idea to promote the effect of some cancer-targeting agents." (PMID 36061184, 2022). "Finally, we investigated the potential correlation analysis between pan-cancer drug resistance and FDX1 expression." (PMID 35991547, 2022). "In addition, the association of FDX1 with TMB and MSI also proves that FDX1 is strongly associated with TME in human cancer." (PMID 36061184, 2022). "Correlation analyses between the CRLRSM and cuproptosis-related genes showed that patients with high FDX1 expression had better prognoses, indicating that high expression of FDX1 might promote cancer cell death." (PMID 36159561, 2022). "In vitro functional assays revealed the prominent anti-cancer role of FDX1 in ccRCC." (PMID 36275737, 2022). "In conclusion, we found FDX1 was a novel biomarker for diverse cancers." (PMID 35991547, 2022). "Our results showed that FDX1 is also strongly involved in cancer immunity." (PMID 36210836, 2022). "Therefore, in our study, we conducted a pan-cancer analysis of FDX1 in different cancers based on the data from the most comprehensive databases and also explored the effect of FDX1 in BLCA, ccRCC, and PCa cells for the first time." (PMID 36210836, 2022). "Taken together, compared to adjacent normal tissues, FDX1 expression is dysregulated in 29 cancers, indicating that it may serve as an oncogene or suppressor in these cancers." (PMID 36210836, 2022). "However, as for FDX1, its role in cancer was poorly understood, and it had only been proven to affect the prognosis of lung adenocarcinoma and mediate its metabolism." (PMID 35991547, 2022). "Therefore, the data on the correlation between DSS and FDX1 expression in various cancers were reanalyzed." (PMID 36061184, 2022). "The survival analysis below, using patient data using the median expression value dichotomy for each cancer type, showed that survival differences were significant across OS-related cancer categories and that patients with high FDX1 expression had a better prognosis in some cancers." (PMID 36061184, 2022). "For example, FDX1 or the cuproptosis signature serves as a prognostic indicator of various cancers, including bladder cancer, hepatocarcinoma, melanoma, and breast cancer, suggesting that its participation in cancer progression deserves a close investigation." (PMID 36611966, 2022).
cancer (continued). "Moreover, FDX1 expression was associated with MMR gene, MSI, TMB, and immune cell infiltration in different cancer types." (PMID 36210836, 2022). "FDX1 expression level in pan-cancers indicated the probable links between FDX1 and cancers." (PMID 35991547, 2022). "Therefore, we aimed to explore the prognostic value of FDX1 in pan-cancer and investigate its potential immune function." (PMID 36210836, 2022). "Recent pan-cancer analysis revealed that FDX1 could be a novel biomarker in the prognosis and immunotherapy in human tumors, which could provide a basis for drug use in certain tumors." (PMID 36212138, 2022). "In subsequent analysis, we only focus on those cancer types sensitive to the FDX1 gene expression." (PMID 36210836, 2022). "Pan-cancer analysis of FDX1 was carried out through TCGA database." (PMID 36105937, 2022). "The expression level of FDX1 in different cancers was explored using the GEPIA2 database." (PMID 36536785, 2022). "Our results revealed that FDX1 expression was positively correlated with the infiltration levels of macrophages M0, neutrophils, and mast cells activated and negatively correlated with mast cells resting in most cancers." (PMID 36210836, 2022). "Therefore, FDX1 may exert dual roles in cancer by either promoting or inhibiting disease progression." (PMID 41853121, 2025). "Therefore, targeting FDX1 is expected to enhance the sensitivity of cancer cells to cuproptosis." (PMID 40897695, 2025). "In addition, expression of FDX1 was correlated with family cancer history." (PMID 37361595, 2023). "Unrelated to the cuproptosis protein in cancer, FDX1 may act as an oncogene." (PMID 38023234, 2023). "Moreover, FDX1 expression varied significantly in different clinical subgroups of KIRC, which suggests that FDX1 might be involved in the growth and progression of cancer." (PMID 37193786, 2023). "Additionally, FDX1 expression varied among the immune subtypes of a given cancer type." (PMID 37193786, 2023). "Additionally, FDX1 might function in the pathogenesis of multiple cancer types via similar molecular mechanisms." (PMID 37298135, 2023). "Furthermore, we explored FDX1 expression in different stage in pan-cancer according to GEPIA2.0." (PMID 36825202, 2023). "The alteration of FDX1 could play a significant role in immunotherapy against cancer." (PMID 37298135, 2023). "However, there are few research on the role of FDX1 expression in various cancers." (PMID 36105937, 2022). "However, as a key regulator in copper-induced cell death, the prognostic and immunotherapeutic value of FDX1 in pan-cancer remains unclear." (PMID 35991547, 2022). "Also, FDX1 can augment the copper-dependent cell death induced by elesclomol and may provide a new idea for increasing the efficacy of several cancer-targeting agents." (PMID 34690780, 2021). "GSS overexpression partially reversed the Vorinostat‐induced molecular changes characteristic of cuproptosis, namely the downregulation of FDX1 and upregulation of HSP70, and partially restored cancer cell proliferation, migration and invasion capacities." (PMID 41431124, 2025). "Our findings highlight the context-dependent roles of these genes—particularly FDX1 and SLC31A1—in cancer progression and immune regulation." (PMID 40601654, 2025). "Quantitative analysis of FDX1 and DLAT expression levels in a broad spectrum of cancer types, correlating these levels with responsiveness to cuproptosis-inducing agents; ii." (PMID 38693584, 2024). "Among these cancers, the cuproptosis key genes, LIAS, FDX1, and DLAT tended to show copy number deletion, while DLD tended to show copy number amplification." (PMID 38573998, 2024). "Evidence has shown that cuproptosis-related genes (e.g. PDXK, FDX1 and LIPT1) can affect the progression of human cancers." (PMID 39652607, 2024).
cancer (continued). "The expression of immune checkpoints was also found to be higher in the high-FDX1 expression group than in the low expression group; this further suggests that FDX1 may be a potential target for cancer immunotherapy, as the immune response is often used as a target for cancer therapy." (PMID 37301546, 2023). "In total, 14 DECRs were identified, of which six regulators (MTF1, DLST, NLRP3, DBT, FDX1, and DLD) were downregulated in cancer tissues." (PMID 36672336, 2023). "We also found high FDX1 expression in the C4 (lymphocyte depleted) and C5 (immunologically quiet) of ACC, PCPG, THCA, LGG, and SARC, and other cancers were shown based on the TISIDB dataset." (PMID 37298135, 2023). "Thus, FDX1-related oxidative phosphorylation may be a novel target for cancer therapy." (PMID 37432054, 2023). "A total of 6 CRSGs were screened out, including CDKN2A, GLS, FDX1, PDHA1, PDHB, and DLD; most of them have been reported in the direct regulation of cuproptosis and cancer progression." (PMID 37287976, 2023). "As three key genes in cuproptosis, FDX1, LIAS, and DLAT, are expected to be the targets in cancer therapy." (PMID 36925927, 2023). "Our analysis of the correlation between FDX1 expression and the IC50 of over 750 anti-cancer drugs was conducted using the GSCA database." (PMID 37193786, 2023). "We used co-expression analysis to analyze the relationship between FDX1 expression and RNA methylation-related genes, mismatch repair (MMR) gene, immune-related genes, and drug sensitivity in these cancers." (PMID 36210836, 2022). "Among the expression of FDX1 in 33 cancer types, KIRC was the only one cancer that was significantly downregulated." (PMID 36536785, 2022). "Our study also found that FDX1 was positively correlated to TME immune, stromal, and ESTIMATE scores in most human cancer types." (PMID 36061184, 2022). "Our results illustrated that FDX1 expression was highly correlated with MMR gene, MSI, and TMB in most cancers." (PMID 36210836, 2022). "For several cancer types, FDX1 expression had a positive correlation with immune cell infiltration, and FDX1 also had a positive correlation with TMB and MSI in some cancer types, linking its expression to the assessment of possible treatment responses." (PMID 36061184, 2022). "In the stemness analysis, STAD was the most striking cancer type, which was positively correlated with the expression of ATP7B, SLC31A1, FDX1, and DLAT." (PMID 36276096, 2022). "The transcriptional levels of DLAT, FDX1, DBT, DLD, PDHB, and GCSH negatively correlate with methylation in part of tumors (> 7 cancer types)." (PMID 36209249, 2022). "After being internalized into cancer cells, the released copper ions (Cu2+) from Cu@IR783-CAI may be reduced to cuprous ions (Cu+) by ferredoxin 1 (FDX1)." (PMID 40880785, 2025). "Among these 13 CRGs, FDX1, DLAT, LIAS, SLC31A1, ATP7A, and ATP7B are well-studied, and therefore, we will explore their expression levels and clinical relevance across different cancers." (PMID 40341098, 2025). "In our retrospective LIHC cohort, there was no marked different between FDX1 expression and clinical information, but the variation trend of FDX1 in gender, family cancer history, and pathologic stage was similar with that in the LIHC cohort." (PMID 37361595, 2023). "Notably, FDX1 showed a low expression in KIRC, and had a decreasing tendency with the development of cancer stages." (PMID 37193786, 2023). "In addition, the correlation between FDX1 and TMB and MSI proved that FDX1 closely related with the TME in human cancers." (PMID 37193786, 2023). "The correlation calculated for all paired samples (33 cancer types) revealed that of the 10 cuprotosis molecules, six (DLAT, DLD, MTF1, CDKN2A, GLS and FDX1) may be negatively regulated by many miRNAs." (PMID 36895378, 2023).